NBPF15 (NBPF member 15)
Synonyms: NBPF16; MGC8902; AB14; AG3
Tractability: PROTAC: ubiquitination databases record sites on it.
Gene: Protein-coding gene on chromosome 1 (144,421,390 to 144,461,676, reverse strand). Ensembl gene ENSG00000266338.
Subcellular location: Cytoplasm
Subcellular location (Human Protein Atlas): Cytosol; Primary cilium; Cytokinetic bridge; End piece; Golgi apparatus; Microtubules; Mid piece; Principal piece; Vesicles
Gene Ontology:
Cellular component: cytoplasm
Genetic constraint (gnomAD): Loss-of-function variants: 39 observed, 31.8 expected, observed/expected ratio (o/e) 1.23, 90% interval 0.95 to 1.6. The synonymous counts are far from expectation, so gnomAD's model fits this gene poorly and the ratio says little. Missense variants: 453 observed, 309.35 expected, observed/expected ratio (o/e) 1.46, 90% interval 1.36 to 1.58. Synonymous variants: 147 observed, 113.32 expected, observed/expected ratio (o/e) 1.3, 90% interval 1.13 to 1.49.
Homologues: Paralogues in human: NBPF14 (98% identical), NBPF10 (97% identical), NBPF26 (97% identical), NBPF12 (96% identical), NBPF19 (95% identical), NBPF20 (95% identical), NBPF9 (93% identical), NBPF8 (93% identical), NBPF1 (84% identical), NBPF11 (75% identical), NBPF3 (65% identical), NBPF4 (41% identical), and 1 more.
Diseases named in the same sentence as NBPF15 in open-access papers:
NBPF15 is named in the same sentence as 1 disease in open-access papers, as found by Europe PMC text mining. Sharing a sentence is not in itself a finding about the gene and the disease. The quoted sentences say what the papers report.
neuroblastoma (1 paper, 2015). Neuroblastoma (NB) is the most common solid, extracranial childhood tumor. "Three fast evolving genes (NBPF11, NBPF12 and NBPF15) that are differentially expressed in both sPTB and PE are part of a neuroblastoma breakpoint (NBPF) gene family that has been shown to exhibit neuron-specific expression and copy number variations." (PMID 26641094, 2015).